PRDX1 (peroxiredoxin 1)
Diseases named in the same sentence as PRDX1 in open-access papers (continued):
Sharing a sentence is not in itself a finding about the gene and the disease.
breast cancer (continued). "PRDX1 could act as a chaperone to enhance the transactivation potential of NF‐κB in ER‐breast cancer cells, and then suppresses tumour cell death." (PMID 27653015, 2017). "However, other studies have shown that elevated mRNA expression of PRDX1 in human breast carcinoma is relevant with higher tumour grade 51, and high expression of cytoplasmic PRDX1 correlated with a great risk of local recurrence after radiotherapy." (PMID 27653015, 2017). "The specific role for PRDX1 in mammary carcinomas is controversial." (PMID 27653015, 2017). "The specific role for PRDX1 in breast cancer is controversial." (PMID 25011585, 2014). "Thus, there is an ongoing need for properly designed studies on the role of PRDX1 in breast cancer that follow the REMARK guidelines for prognostic biomarkers." (PMID 25011585, 2014). "Based on our accumulated data, we hypothesize that PRDX1 shields the dependence of mammary tumors on estrogen-mediated growth stimulation, which eventually is of benefit for the patient." (PMID 25011585, 2014). "Conversely, several lines of evidence suggest that PRDX1 may act as a tumor suppressor in breast cancer." (PMID 25011585, 2014). "We identify PRDX1 expression levels as an independent marker of favorable outcome in ER-positive tumors and elucidate a unique role for PRDX1 in maintaining ERα expression in breast cancer cells subjected to oxidative stress." (PMID 25011585, 2014). "However, further investigation of the mechanism of miR-510 mediated negative regulation of PRDX1 is necessary to fully understand their role in tumorigenesis and breast cancer progression." (PMID 23971998, 2013). "Likewise, when a range of breast cancer cell lines were analysed by western blotting, we noticed that PRDX1 and PRDX2 protein content is highly upregulated in breast cancer cells, as compared to primary human mammary epithelial cells HMEC and non-malignant, mammary tissue-derived MCF-10A cell line." (PMID 30287919, 2018). "Therefore, we examined whether breast cancer cell lines exposed to oxidative stress had altered levels of these estrogen and breast cancer signaling proteins, and if modulation of PRDX1 expression could alter any oxidative stress-induced signaling changes." (PMID 25011585, 2014). "First, targeting PRDX1 enhanced the sensitivity of AML cells to chemotherapy drug, and similar findings have been observed in breast cancer." (PMID 40825764, 2025). "Overall, these studies suggest that PRDX1 and PRDX2 promote breast cancer cell survival via induction of radio/chemoresistance and inhibition of oxidative stress-induced cell death." (PMID 40214422, 2025). "Prdx1 knockdown increased the apoptosis rate of HBXIP OE/Nrf2 KD and HBXIP KD/Nrf2 OE breast cancer cells." (PMID 35027562, 2022). "The staining intensity of HBXIP was positively correlated with that of Prdx1, and the Prdx1 and HBXIP expression levels were significantly correlated with the status of metastasis in breast cancer tissues." (PMID 35027562, 2022). "The HBXIP/Nrf2 axis promotes ECM-detached breast cancer cell survival by reducing cellular ROS accumulation and stabilizing Prdx1, which inhibits the release of JNK1 from Prdx1-GSTπ-JNK heterotrimeric complexes and prevents JNK1 activation." (PMID 35027562, 2022). "Our previous work has shown peroxiredoxin-1 (PRDX1), one of major antioxidant enzymes, to be a biomarker in human breast cancer." (PMID 30287919, 2018). "Herewith, we investigated the effects of pharmacologic inhibition of PRDX1/2 with ADNT in combination with prooxidant agents to test their effects on parental MCF-7 and ZR-75-1 breast cancer cell lines." (PMID 30287919, 2018). "PRDX1 downregulation significantly impaired the growth rate of MCF-7 and ZR-75-1 breast cancer cells." (PMID 30287919, 2018). "Repression of PRDX1 expression leads to high levels of ROS‐induced phosphorylation of p38 MAPKα, and promotes H2O2‐induced senescence in breast cancer cells." (PMID 27653015, 2017).
breast cancer (continued). "Overexpression of miR‐510 leads to decreased PRDX1, which, in turn, increases the activity of PI3K/Akt pathway and promoted cell and tumour growth in breast cancer." (PMID 27653015, 2017). "The GLUT3 mRNA expression level was similarly increased by arsenite in the MDA-MB-231 breast cancer cell line lacking the PRDX1 gene." (PMID 38067110, 2023). "PRDX1 belongs to the PRDX family and is a 23-kDa stress-induced macrophage redox protein that has multiple functions, including managing hydrogen peroxide-mediated oxidative stress in vitro and in vivo, and is a potential target for breast cancer treatment." (PMID 33503027, 2021). "In breast cancer cells, SIRT2 could stop the peroxiredoxin-1 activity, increase the responsiveness of breast cancer cells to reactive oxygen species stimulated DNA damage and so encourage the apoptosis of cancer cells." (PMID 33705642, 2021). "High dose H2O2 results in dissociation of PRDX1 from PTEN and PTEN inactivation, which might occur more frequently in the microenvironment of breast cancer compared to the normal breast, since ROS are known to be higher in cancer tissues." (PMID 31419957, 2019). "Hereby, similarly to MCF-7, we observed a significant decrease in the growth rate of ZR-75-1 breast cancer cells harboring the shRNA against PRDX1 (ZR-75-1 shPRDX1), but not PRDX2 (ZR-75-1 shPRDX2), as compared to the controls (ZR-75-1 parental and shNTC)." (PMID 30287919, 2018). "Peroxiredoxin-1 (Prdx1), a member of the thioredoxin (Txn) system, is overexpressed and correlates with poor prognosis in pancreatic cancer patients and can suppress Kras signaling through redox-mediated inhibition of ERK and AKT in lung and breast cancer." (PMID 29190947, 2017). "Peroxidase enzymes are considered to be important in eliminating the peroxides generated during cancer metabolism, and PRDX1 and 2 in MCF-7 breast cancer cells exhibit important functions as inhibitors of cell death during the cellular response to oxidative stress." (PMID 24932247, 2014). "Based on the expression level of internal control β-actin, several human cancer cell lines such as HepG2 (hepatocellular carcinoma), SKBR3 (breast cancer), SKOV3 (ovarian carcinoma) and A549 (lung epithelial adenocarcinoma) exhibited a strong reactivity to anti-Prdx1." (PMID 24009050, 2013). "Noh and colleagues reported that PRDX1, PRDX2 and PRDX3 were overexpressed in breast cancer tissues, suggesting that PRDXs had a proliferative effect and might be related to cancer development or progression." (PMID 17980029, 2007). "Karihtala and colleagues observed that staining for PRDX2 and PRDX6 was negative in half of breast cancer cases, whereas PRDX1, PRDX3, PRDX4 and PRDX5 showed stronger expression levels." (PMID 17980029, 2007). "Neumann and colleagues found that mice lacking PRDX1 have a shortened lifespan partly owing to several malignant cancers, including breast cancer." (PMID 17980029, 2007). "Breast carcinoma patients with different risks of cancer progression or death were filtered into four groups (HBIXP high expression group, Prdx1 high expression group, HBXIP/Prdx1 high group, and HBXIP high/Prdx1 low group) based on HBXIP and Prdx1 expression z scores." (PMID 35027562, 2022). "The previous research from our group and others suggests that PRDX1 protein is upregulated in breast cancer as compared to the non-malignant mammary cells, and, by stabilizing the redox balance, it can inhibit the progression of breast cancer into more aggressive forms." (PMID 32316111, 2020). "In addition, the mean PRDX1 expression in CTCs (29.34 ± 24.6) was numerically, but not statistically higher than that observed in breast cancer cell lines and in the normal PBMCs (15.9 ± 3.62)." (PMID 31370904, 2019).
breast cancer (continued). "The reintroduction of PRDX1 into breast cancer cell lines without its regulatory 3'UTR confirmed that miR-510 was mediating its migratory phenotype at least in part through the negative regulation of PRDX1." (PMID 23971998, 2013). "Taken together, these findings imply again that mainly PRDX1, but not PRDX2, plays a substantial role in exogenous H2O2 metabolism in breast cancer cells and, hence, is protecting these cells against toxicities of the H2O2-stimulated oxidative stress." (PMID 30287919, 2018). "Importantly, when a close homolog of PRDX1, i.e., PRDX2, was genetically targeted, there was no amplification of Asc-induced toxicity against breast cancer cells." (PMID 32316111, 2020). "Our current study indicates the superior role for PRDX1, but not PRDX2, in curtailing oxidative stress by breast cancer cells and suggests that this molecule could be further examined as a potential therapeutic target in this disease." (PMID 30287919, 2018).
colorectal cancer (24 papers, 2011 to 2025). A primary or metastatic malignant neoplasm that affects the colon or rectum. "PRDX1 demonstrated the highest diagnostic efficiency for colorectal cancer and the lowest for gastric cancer." (PMID 37781072, 2023). "We discovered that inhibiting PRDX1 by Celastrol or its analogs caused ROS elevation and then suppressed the proliferation of colorectal cancer cells, while NAC treatment reversed the apoptotic phenotypes." (PMID 36732502, 2023). "Obviously, PRDX1 has general diagnostic value for esophageal cancer, liver cancer, and colorectal cancer, while its diagnostic value for gastric cancer is relatively low." (PMID 37781072, 2023). "PRDX1 demonstrated the highest diagnostic efficacy for colorectal cancer." (PMID 37781072, 2023). "Therefore, PRDX1 demonstrates the highest diagnostic efficiency for colorectal cancer and the lowest for gastric cancer." (PMID 37781072, 2023). "Peroxiredoxin 1 (PRDX1) overexpression in colorectal cancer (CRC) correlates with poor prognosis and reduced T‐cell infiltration." (PMID 41306557, 2025). "Compounds targeting ROS-manipulating protein PRDX1 revealed that decreased levels of PRDX1 suppressed colorectal cancer cell proliferation even under adequate dietary iron concentrations." (PMID 38732562, 2024). "Celastrol upregulates the reactive oxygen species (ROS) level and promotes apoptosis in colorectal cancer (CRC) cells by inhibiting the antioxidant activity of PRDX1." (PMID 39590360, 2024). "Using our new computational tool OTTER combined with experimental assays, PRDX1 was identified as the primary target protein of Celastrol in colorectal cancer, for its ROS-dependent anti-tumor activity." (PMID 36732502, 2023). "The anti-tumor efficacy of Celastrol and 19-048 was significantly diminished on xenograft nude mice bearing PRDX1 knock-down colorectal cancer cells." (PMID 36732502, 2023). "Then peroxiredoxin 1 (PRDX1) was identified as the ROS-manipulating target protein of Celastrol in colorectal cancer." (PMID 36732502, 2023). "We aim to discuss the role of miR-431-5p in colorectal cancer (CRC) progression via regulating peroxiredoxin 1 (PRDX1)." (PMID 35460420, 2022). "In colorectal cancer, gastric cancer and lung cancer, PRDX1 has been proven to promote tumor metastasis, but PRDX1 has also been pointed out to act as a tumor metastasis suppressor in hepatocellular carcinoma and osteosarcoma." (PMID 31956363, 2020). "In colorectal cancer, PRDX1 was also reported to be overexpressed in the tumor tissues at protein level in previous studies 32, 34 with predominantly cytoplasmic localization." (PMID 32231717, 2020). "PRDX1 has been reported to be an inflammatory marker for colorectal cancer progression." (PMID 39951474, 2025). "This variability in the ability to invade and migrate tumor cells across different CRC cell lines suggests that PRDX1 might predict prognosis and serve as a potential therapeutic target, regulating tumor metastasis and angiogenesis in colorectal cancer." (PMID 37781072, 2023). "Our findings reveal that the side effects of Celastrol could be reduced via structural modification, and PRDX1 inhibition is promising for the treatment of colorectal cancer." (PMID 36732502, 2023). "Both Celastrol and compound 19-048 showed decreased IC50 values in gPRDX1 SW620 cells, suggesting that knockdown of PRDX1 could enhance the sensitivity of colorectal cancer cells to Celastrol and compound 19-048." (PMID 36732502, 2023). "To validate that PRDX1 is the dominant target protein for the cell cycle arrest and apoptosis induced by Celastrol and compound 19-048 in colorectal cancer cells, we generated PRDX1-knockdown (gPRDX1) SW620 cells by CRISPR-Cas9 system, with the scrambled negative sgRNA as control (gNS)." (PMID 36732502, 2023).
colorectal cancer (continued). "Moreover, targeting peroxiredoxin-1 is considered as one of the novel strategies for treatment of colorectal cancers." (PMID 35327385, 2022). "Peroxiredoxin-1 is reported to promote metastasis and angiogenesis in colorectal cancers." (PMID 35327385, 2022). "However, the role of overexpression of PRDX1 in colorectal cancer (CRC) was elusive." (PMID 39430237, 2024). "The results provided direct biochemical evidence that AIN increases the thermal stability of PRDX1 and PRDX2 in intact colorectal cancer cells, which confirmed their role as cellular targets." (PMID 40362180, 2025). "MS-CETSA was also used to reveal that ainsliadimer A targets PRDX1 and PRDX2, which induces reactive oxygen species (ROS)-mediated apoptosis in colorectal cancer cells." (PMID 40362180, 2025). "Prior research has observed increased expression levels of PRDX1 in numerous cancer types, including non‐small cell lung cancer (NSCLC), ovarian cancer (OC), prostate cancer, colorectal cancer, and gastric cancer." (PMID 40281661, 2025). "They concluded that AIN induces oxidative stress and mitochondrial dysfunction by inhibiting PRDX1 and PRDX2, which results in ROS-mediated apoptosis in colorectal cancer cells." (PMID 40362180, 2025). "In colorectal cancer (CRC), high PRDX1 expression correlates with tumor invasiveness, metastasis, and chemotherapy resistance, and its role in immune evasion and chemotherapy resistance makes it a potential therapeutic target." (PMID 40256656, 2025).
lung cancer (24 papers, 2006 to 2025). A malignant neoplasm involving the lung. "Previous studies in other cancers, including breast and lung cancer, have implicated PRDX1 in promoting epithelial–mesenchymal transition (EMT), immune evasion, and chemotherapy resistance." (PMID 41019038, 2025). "Under ionizing radiation, PRDX1 associates with the GST-pi/JNK1 complex in human lung cancer cells, thereby inhibiting JNK activity." (PMID 31419957, 2019). "Other DEPs including aldo-keto reductase family 1 member B1 (AKR1B1), cyclin-dependent kinase 2 (CDK2), death associate protein kinase-1 (DAPK1), peroxiredoxin-1 (PRDX1) and aldehyde dehydrogenase mitochondrial (ALDH2) are associated with lung cancer." (PMID 40088196, 2025). "In lung cancer (LC), PRDX1 protects cancer cells from damage by reducing oxidative stress and plays a significant role in chemotherapy resistance." (PMID 40256656, 2025). "Aberrant PRDX1 expression occurs in numerous cancers, particularly in breast, oesophageal, and lung cancers (Ding, Fan & Wu, 2017)." (PMID 38213773, 2024). "For instance, several studies have indicated that PRDX1 can function as a pro-oncogene in lung cancer and soft tissue sarcoma." (PMID 36969053, 2023). "PRDX1 has been reported to be an independent prognostic factor for disease recurrence and reduced survival in non–small-cell lung cancer and gastric cancer." (PMID 31429766, 2019). "Increased ROS accumulation inhibits PRDX1 expression and induces lung cancer cell death after vitK3 treatment." (PMID 27653015, 2017). "1q is amplified in approximately 35.5% of lung cancer 45, and the PRDX1 expression is significantly elevated in lung cancer patients as compared with patients with benign lung disease." (PMID 27653015, 2017). "In addition, previous data revealed PRDX1 upregulation as an independent prognostic factor for disease recurrence and a therapeutic target in lung cancer." (PMID 38213773, 2024). "Recent studies have found that PRDX1 and/or PRDX1‐regulated ROS‐dependent signalling pathways play an important role in the progression and metastasis of human tumours, particularly in breast, oesophageal and lung cancers." (PMID 27653015, 2017). "Therefore, the tumor growth and augmentation of radio-sensitivity by decreasing Prdx1 expression in lung cancer cell lines was inhibited." (PMID 24009050, 2013). "We highlighted specific proteins, including AKR1B1, CDK2, DAPK1, PRDX1 and ALHD2 with potential as biomarkers for radon-related lung cancer." (PMID 40088196, 2025). "The proteins such as AKR1B1, CDK2, DAPK1, PRDX1 and ALDH2 show potential as biomarkers or therapeutic targets for radon-related lung cancer after further validation." (PMID 40088196, 2025). "The mRNA levels of PRDX1, PRDX2, PRDX3, PRDX5, and PRDX6 showed an excellent correlation with the OS of lung cancer patients." (PMID 32908916, 2020). "Knockdown of PRDX1 in lung cancer cells significantly inhibits transforming growth factor β1 (TGF‐β1)‐induced epithelial–mesenchymal transition (EMT) and cell migration, whereas PRDX1 overexpression enhances TGF‐β1‐induced EMT and cell migration." (PMID 27653015, 2017). "Lastly, A549 lung carcinoma cells that overexpress either isoform of WDR23 have reduced expression of the NRF2 targets GSTA and PRDX1, which are often induced in cancer cells and have been identified as potential targets for directed therapy." (PMID 28453520, 2017). "Interestingly, PRDX1 physically interacts with GSTpi and suppresses JNK release/activation from the GSTpi‐JNK complex after γ‐ray radiation exposure in human lung cancer 1170i cells." (PMID 27653015, 2017). "Knockdown of PRDX1 or PRDX4 significantly reduced the activation of c-Jun and thus repressed AP-1 mediated promoter activity, which may contribute to the changes of lung cancer cell phenotype." (PMID 26061816, 2015).